LAG3 (lymphocyte activating 3)
Diseases named in the same sentence as LAG3 in open-access papers (continued):
Sharing a sentence is not in itself a finding about the gene and the disease.
tumor (continued). "In humans, LAG-3+ pDCs in melanoma have been implicated in tumor-associated immunosuppression where tumor-associated MHC-II expression induces TLR-independent activation, production of inhibitory cytokines and recruitment of myeloid derived suppressor cells (MDSCs)." (PMID 30788290, 2019). "Probably for that reason, LAG-3-deficient mice present a reduced ability to control tumor growth." (PMID 26347741, 2015). "In conclusion, our findings suggest that the immune checkpoint LAG3 is closely associated with immune activation in the ESCC tumor microenvironment in terms of both overall content and spatial relationship and may serve as a potential predictor of overall survival and CCRT efficacy in ESCC patients." (PMID 40411616, 2025). "In particular, it is still an open question whether the immune-enhancing effects of HLB-apt are mediated through the blockade of inhibitory signal transduction pathways associated with LAG-3 or if they primarily function as a molecular bridge physically connecting Jurkat cells to tumor cells." (PMID 40761795, 2025). "Thus, a gene expression profile associated to PDCD1/LAG3 could be extracted from tumors which indicated immune dysfunctionality, possibly from tumor-infiltrating T-cells." (PMID 39030301, 2024). "In addition, LAG3 expression could be associated with the tumor-infiltrating immune cells and might be an underlying predictive biomarker for cancer immunotherapeutic response." (PMID 38115039, 2023). "T cells within the tumor microenvironment often show features of functional exhaustion and this is typically associated with expression of programmed cell death protein 1 (PD-1), often in association with additional checkpoint markers such as Tim-3, LAG-3, or CTLA-4." (PMID 36689623, 2023). "Furthermore, we found higher expression of LAG3 in association with higher tumor grades." (PMID 34267742, 2021). "Therefore, period post-infection could be associated with viral load and tumor development as well as the upregulation of PD-1 and LAG-3." (PMID 29914540, 2018). "A member of the immunoglobulin super-family, Lymphocyte Activation Gene 3 (LAG3) is expressed by subsets of both activated and exhausted lymphocytes and plasmacytoid dendritic cells, and plays a key role in regulating the effector activity of tumor-associated lymphocytes." (PMID 25763356, 2015). "To address this limitation, we developed tobemstomig, a novel bispecific antibody to preferentially and simultaneously block PD-1 and LAG-3 in cis on tumor-specific CD8 TILs, while sparing Tregs." (PMID 42284551, 2026). "Localized delivery of anti-LAG-3 antibodies to the tumor microenvironment promoted tumor control while reducing the overall number of animals experiencing severe irAE compared with those receiving systemic LAG-3 blockade." (PMID 41629131, 2026). "Before challenge with tumor cells, the expression of exhaustion-associated surface markers—including PD-1, TIM-3, LAG-3, TIGIT, and CTLA-4—was comparably low between iCD4+ and iCD8+ T cells." (PMID 41484912, 2026). "LAG-3 inhibition has been shown in an immunocompetent mouse model to decrease tumor burden and increase the efficacy of CD8+ T-cell immune function." (PMID 41431358, 2026). "Lymphocyte-activation gene 3 (Lag3) is an inhibitory checkpoint receptor that contributes to T-cell exhaustion and tumor immune evasion." (PMID 42109893, 2026). "CONCLUSIONS: LAG3+ TAMs are expanded in GC through a tumor-macrophage feedback circuit driven by exosomal miR-151a-5p, resulting in CD8+ T-cell dysfunction and immune resistance." (PMID 41923099, 2026). "LAG-3 expression in tumor-infiltrating CD8+ T-cells was significantly reduced in the IPI-549/PD-L1 dual treatment group compared to single and vehicle control treatment groups." (PMID 41431358, 2026).
tumor (continued). "Remarkedly, the FGF/FGFR1/NOTCH1 within RB1 variant group has a dramatically higher inner‐tumor CD8+ T cell infiltration, following more CD8+PD‐1‐LAG3‐ non‐exhausted T cells and CD8+PD‐1+LAG3‐ exhausted T cells." (PMID 40001320, 2025). "Pathways such as PD-1/PD-L1, CTLA-4, and LAG-3 suppress T cell function and enable immune escape, ultimately accelerating tumor progression and dissemination." (PMID 40808954, 2025). "Flow cytometry of single-cell suspensions from tumour tissues further hints that CX-5461 administration induced Lag3 in CD8+ T cells." (PMID 40646287, 2025). "Acquired resistance mechanisms include loss of HLA expression, upregulation of alternate immune checkpoints (such as TIM-3 and LAG-3), and dynamic remodeling of the tumor’s metabolic environment." (PMID 41373587, 2025). "The results showed that LAG-3 antibody treatment abolished the enhancement of tumor growth induced by DCDC2 overexpression in humanized mice, both in the tumor volume and the tumor weight." (PMID 40533767, 2025). "Altogether, this suggests that such an increase in LAG-3 results from prolonged inflammation and constant stimulation with tumour cells." (PMID 40136700, 2025). "Co-expression of LAG-3/TIM-3 in 89% of tumor-infiltrating lymphocytes correlates with 8.3-month shorter metastasis-free survival." (PMID 41268982, 2025). "Triple immunotherapy with anti-PD-1 mAb, a STING agonist, and anti-LAG-3 mAb further enhanced efficacy compared to any dual immunotherapy regimen, and treatment efficacy was linearly associated with [68Ga]Ga-NOTA-C25 tumor uptake." (PMID 40796887, 2025). "Specifically, co-culturing T cells with tumor cells alone resulted in 30% of T cells expressing LAG3." (PMID 41019041, 2025). "The EOMES GRN, encompassing CD8A, GZMK, STAT5A, CXCR3, and LAG3, integrates cytotoxic effector functions, migratory capacity, and checkpoint regulation—features critical for sustained anti-tumor immunity." (PMID 40520886, 2025). "LAG-3 interacts with ligands such as major histocompatibility complex II (MHC-II) expressed by tumor or innate immune cells, and fibrinogen-like protein 1 (FGL-1), highly expressed in some tumors." (PMID 40234667, 2025). "The radioactivity distribution of 99mTc‐HYNIC‐αLAG‐3 predominantly encompassed blood, liver, spleen, lung, and kidney, with no notable variance among LAG‐3+ A549, LAG‐3− A549, and blocked LAG‐3+ A549 mice (non‐tumor tissues: p > 0.05)." (PMID 39513410, 2025). "This study aimed to demonstrate the utility of [68Ga]Ga-NOTA-C25 PET imaging for detecting LAG-3 upregulation in TILs in Hepa1-6 tumor-bearing mice treated with anti-PD-1 mAb and STING agonists." (PMID 40796887, 2025). "The dual therapy with anti-LAG-3 and anti-PD-1 antibodies counteracts these effects and potentially eradicate tumours." (PMID 39901202, 2025). "Our results revealed distinct patterns that vary between tumor types but globally resemble those of the Tex markers, and in some cases, they are expressed even higher than some Tex cell markers, like LAG3, PD1, TIGIT, and CXCL13." (PMID 40076932, 2025). "DN T cells were predominantly Vδ2-γδ T cells that prove their anti-tumor action and express PD-1 and lymphocyte activation gene 3 (LAG3); their phenotype describes an immune exhausted sub-population." (PMID 40227764, 2025). "The antitumor activity of cytotoxic LAG-3+ CD8+ T cells is generally reduced, and the expression of LAG-3 in regulatory T cells enhances their immunosuppressive functions and promotes tumor growth." (PMID 39751894, 2025). "Expression of LAG-3 is upregulated on immune cells within CRC tumours, and high expression is associated with poor tumour differentiation, advanced stage, lymph node involvement, and invasion depth." (PMID 40016550, 2025). "FGL1, which was secreted at low levels in normal liver but was abnormally high expressed in a variety of cancers, inhibits T cell activation and promotes tumor immune escape by binding LAG-3." (PMID 40276056, 2025).
tumor (continued). "Expression of TIM-3 and LAG-3 on tumor-infiltrating lymphocytes (TILs) was significantly higher in SCC (median ScoreTIM-3: 14, median ScoreLAG-3: 1) compared to ADENO (median ScoreTIM-3: 1, median ScoreLAG-3: 0; p < 0.001 for both VH)." (PMID 40647508, 2025). "In melanoma patients, tumor lactate levels positively correlate with the proportion of PD-1+ LAG-3+ CD8+ T cells (r=0.82, p<0.001), indicating that lactate plays a crucial role in driving T cell exhaustion." (PMID 41415289, 2025). "In line, expression of LAG-3, another immune checkpoint receptor, was enhanced in tumor-bearing mice even though to a lower extent than PD-1." (PMID 39751916, 2025). "Recent studies of metastatic OS lung tissues reveal an immune-cold TME with enriched PDL1-, LAG3-, and TIM3-expressing tumor-infiltrating lymphocytes, M2, and MDSC at the tumor periphery associated with poorer survival." (PMID 40940877, 2025). "Within the context of cancer immunotherapy, LAG-3 inhibitors such as relatlimab are employed to augment anti-tumour immunity by reversing T-cell exhaustion and restoring effector T-cell function." (PMID 40895685, 2025). "The association between PIEZO1 and tumor microenvironment scores (Stromal, Immune, ESTIMATE) or immune checkpoint markers (CD274, CTLA4, LAG3, PDCD1, PDCD1LG2) were analyzed using the R language." (PMID 40977743, 2025). "The anti-tumor effect is associated with down-regulation of mRNA relating to several IC molecules, including TIGIT, PD-1 and LAG-3." (PMID 40890162, 2025). "The energy-depleted, ROS-rich environment within tumors further promotes the expression of inhibitory receptors such as PD-1, TIM-3, and LAG-3, reinforcing the exhausted phenotype of T cells and diminishing their capacity to persist and eliminate tumor cells." (PMID 40475782, 2025). "The high expression of LAG-3 on Tregs enhances their immunosuppressive capabilities, further promoting tumor immune evasion." (PMID 40918452, 2025). "In summary, PD-1 and CTLA-4 were primarily expressed in lymphocytes, whereas PD-L1 and LAG-3 were present in both tumor and lymphocyte cells." (PMID 40061944, 2025). "TIGIT overexpression in CD8+ and CD4+ T cells is correlated with HNSCC progression and a poor treatment response, and TIGIT/PD-1/LAG-3 axis activation is correlated with tumor progression and the development of an immunosuppressive microenvironment." (PMID 40805285, 2025). "The expression of PD-1 and LAG-3 on CD8 T-cells within the baseline tumor biopsies of patients with DLBCL was assessed using immunofluorescence in the ELM-1 cohort of patients treated with odronextamab." (PMID 39858099, 2025). "More specifically, Du and colleagues reported enhanced anti-tumor efficiency in a TNBC based mouse model treated with LAG3 and PD-1 dual blockade." (PMID 40148963, 2025). "While CTLA-4 is responsible for inhibiting the activation of naïve T-cells in the lymph node during the initial immune response, PD-1/PD-L1 and LAG-3 play significant roles in the tumor microenvironment." (PMID 40108693, 2025). "In MC38 colon carcinoma and B16 melanoma models, LAG3KR mice phenocopied LAG3 knockouts, showing markedly inhibited tumor growth with 50% achieving complete tumor regression and enhanced infiltration of IFN-γ+ T cells in the tumor microenvironment (TME)." (PMID 41186850, 2025). "CD8+TIM3+ and CD8+LAG3+ cells were predominantly located in the tumor parenchyma of recurrent/metastatic patients but localized to the stroma in non-recurrent/non-metastatic patients." (PMID 40710213, 2025). "When paired with an immune checkpoint blockade in vivo, BRD4 inhibitors significantly improved the efficacy of anti–PD-L1 and anti–LAG-3 therapy, resulting in overall reduced tumor growth and improved survival." (PMID 40762981, 2025). "LAG-3 aptamers are also gaining attention due to their potential to modulate immune suppression within the tumor microenvironment." (PMID 40870970, 2025).
tumor (continued). "Consistently, EZH2i promoted T cells activation (Granzyme B, IFNγ) and inhibited their exhaustion (LAG3) in tumor treated with chemotherapy, with similar phenomena as chemoimmunotherapy." (PMID 40708008, 2025). "The same concept was applied to target PD1, TIM3 and LAG3 in CAR-T cells using short hairpin RNA cluster to enhance tumor control." (PMID 41181132, 2025). "Co-culturing T cells with tumor cells induced LAG3 expression in 30% of T cells, a percentage that significantly dropped to 21% and 10% with the addition of 0.5 μM and 1 μM arsenic sulfide, respectively." (PMID 41019041, 2025). "With regards to dual inhibition of LAG-3 and PD-1, early-stage clinical data have shown improved anti-tumour responses in patients with advanced solid tumours treated with anti-LAG-3 plus anti-PD-1 combinations." (PMID 40016550, 2025). "In contrast, resistance is associated with upregulation of TIM3, LAG3, TIGIT, and PD-1 expression on T cells, and infiltration of the tumor with immunosuppressive TREM2+ macrophages and monocytes." (PMID 40027748, 2025). "Currently, over 50 LAG-3 targeting agents are being explored in preclinical and clinical studies, aiming to enhance anti-tumor immune responses." (PMID 41233805, 2025). "In one study, the expression of LAG3 on tumor-infiltrating lymphocytes (TILs) was reported to be upregulated after microwave ablation (MWA) treatment." (PMID 41002563, 2025). "Lymphocyte activation gene 3 (LAG-3), the third-generation immune checkpoint receptor, is highly up-regulated on exhausted T cells in the tumor microenvironment." (PMID 40510353, 2025). "In line with the literature, we observed increased levels of PD-1+, GITR+ and LAG-3+ T cells in the tumor and in the periphery of tumor-bearing mice." (PMID 39751916, 2025). "The ligands for LAG-3 in the tumor microenvironment are MHC II (major histocompatibility complex class II), galactose-lectin-3 (Galectin-3), hepatic sinusoidal endothelial cell lectin (LSECtin), fibrinogen-like protein 1 (FGL1), and α-synuclein." (PMID 40362333, 2025). "MHC class II expressed on tumor cells suppresses T-cell function through binding to LAG-3, while it also activates an antitumor immune response by presenting tumor antigens to CD4-positive T cells." (PMID 40801643, 2025). "Gal-3 also binds checkpoint receptors such as LAG3 on T cells, further dampening anti-tumor immunity." (PMID 41153387, 2025). "Perforin-1 (PRF1), a cytotoxic molecule known to enhance anti-tumor immune responses, showed a positive correlation with LAG3 expression in this study." (PMID 40411616, 2025). "The results revealed that PDCD1/PD-1 and LAG3 exhibited a high level of surface expression on CD8+ T cells in tumor tissues with elevated circGRAMD4 expression." (PMID 40373256, 2025). "Functional experiments demonstrated that LAG3 inhibits tumor proliferation and migration, while single‐cell sequencing identified its predominant expression in Treg and CD8+ T cells, implicating its role in immune regulation." (PMID 41025546, 2025). "It is well‐documented that upregulated LAG‐3 expression reduces cytokine production and T‐cell proliferation, resulting in T‐cell dysfunction during tumor stimulation and chronic immune challenges." (PMID 40091778, 2025). "Although anti-LAG3 monotherapy has generally demonstrated limited antitumor efficacy, the combination of anti-LAG3 and anti-PD-1 has demonstrated synergistic activity in tumor models, leading to the development of the first anti-LAG3 mAbs, relatlimab." (PMID 41303538, 2025). "A direct comparison of the two inhibitors revealed a slight superiority of anti-LAG-3 over anti-PD-L1, potentially due to the presence of LAG-3+T-cells at early tumor stages, whereas PD-L1 plays a more functionally relevant role at later stages." (PMID 40674934, 2025).
tumor (continued). "Several gene signatures (FOXP3, Helios, neuropilin-1, CTLA-4, PD-1 and LAG-3) are also found to be upregulated in TIGIT+ Tregs within the tumor microenvironment (TME), turning Tregs to a more immunosuppressive phenotype." (PMID 40890162, 2025). "While LAG-3 blockade is associated with improved NK cell responses, the impact of LAG-3 expression by NK cells on tumor control is unclear." (PMID 40849493, 2025). "UAMOCS2 exhibited an enrichment of stromal and immunosuppressive cells, including MDSCs and TITR (tumor‐infiltrating T regulatory cell), and LAG3 low expression." (PMID 39927613, 2025). "For instance, PD-1/LAG-3 are often co-expressed on tumor-infiltrating lymphocytes (TILs) in “inflamed” tumors, where pre-existing immunity is physiologically regulated rather than suppressed." (PMID 40809844, 2025). "Among immune checkpoints, lymphocyte activation gene‐3 (LAG‐3) emerges as a key immunosuppressive receptor that inhibits effector T‐cell function, promoting tumor immune escape." (PMID 40091778, 2025). "Downregulation of AL031775.1 in T cells resulted in a significant decrease in T cell proliferation, an increase in apoptosis, and a reduced capacity for tumor cell lysis, accompanied by elevated expression of immune checkpoints LAG3, CTLA4, and PD1." (PMID 40066455, 2025). "Panel 3 complements Panels 1 and 2, as it was designed to assess LAG-3 expression on cytotoxic T cells (CD8+LAG-3+), macrophages (CD68+LAG-3+), NK cells (CD56+LAG-3+), Treg cells (FOXP3+LAG-3+) and tumour cells (SYN+LAG-3+)." (PMID 41285059, 2025). "Although synergistic tumor suppression via PD-1 and LAG-3 inhibition has been reported, PD-1 is considered to play a primary role in the suppression and elimination of MC-38 cells." (PMID 40687785, 2025). "Further research should examine CXCR5 and LAG‐3 expression in lymphoid tissues to better understand their role in the tumor microenvironment." (PMID 40091778, 2025). "Increased production of several cytokines including IFN-γ and TNFα has been observed as well as a reduction of tumor volume in those preclinical tumor mouse model, supporting the therapeutic benefit of LAG-3 and PD-1 blockade." (PMID 41051510, 2025). "Following the injection of sh-TBX21, no significant changes were observed on the clusters of PD-1+CD4+ T cells, Tim-3+CD4+ T cells, Lag-3+CD4+ T cells, PD-1+CD8+ T cells, Tim-3+CD8+ T cells, and Lag-3+CD8+ T cells in tumor tissues." (PMID 41573646, 2025). "In a PDAC murine model, the KRAS G12D reversible inhibitor, MRTX1133, when combined with CXCR1/2 inhibitor and anti-LAG3 and anti-41BB antibodies yielded complete tumor regression and prolonged survival in 36% of mice at 6 months." (PMID 40227779, 2025). "Research has found that the co-expression of LAG-3 and PD-1 is highly prevalent in tumor-infiltrating T cells, and these co-expressing T cells display the most severe exhaustion phenotype." (PMID 41415289, 2025). "Dual programmed cell death protein (ligand)-1 (PD-[L]1) and lymphocyte-activation gene-3 (LAG-3) blockade has demonstrated improved anti-tumour response in some advanced solid tumours." (PMID 40016550, 2025). "In contrast, acquired resistance arises after an initial response to therapy, when the tumor adapts by upregulating alternative immune checkpoints like TIM-3 or LAG-3 or by recruiting immunosuppressive cells like Tregs, MDSCs, and TAMs." (PMID 40565559, 2025). "Recent clinical trials have demonstrated that targeting LAG-3 with monoclonal antibodies, such as relatlimab, in combination with PD-1 inhibitors can enhance T-cell activation and promote a more robust anti-tumor immune response." (PMID 40223940, 2025). "Functionally, LAG-3 engagement inhibits T cell activation and proliferation, facilitating tumor immune evasion." (PMID 41300994, 2025). "Among them, LAG3 has emerged as a key regulator of T cell exhaustion and a promising target in next-generation tumor immunotherapy." (PMID 41614836, 2025).